BBS10 (Bardet-Biedl syndrome 10)
Diseases named in the same sentence as BBS10 in open-access papers:
BBS10 is named in the same sentence as 52 diseases in open-access papers, as found by Europe PMC text mining. Sharing a sentence is not in itself a finding about the gene and the disease. The quoted sentences say what the papers report.
Bardet-Biedl syndrome (21 papers, 2012 to 2025). A ciliopathy with multisystem involvement. "Of the 3 patients (4.3%) with a suspected ciliopathy, one (#42) was genetically diagnosed with Bardet–Biedl syndrome, as she presented with a biallelic BBS10 variant." (PMID 39384646, 2025). "BBS9 and BBS10 have been reported as causative genes in Bardet–Biedl syndrome, and their proteins are thought to play a role in protein trafficking and the function of photoreceptors that connect cilia to outer segments." (PMID 37298549, 2023). "BBS10 (Bardet-Biedl syndrome 10): Bardet-Biedl syndrome 10 (vision loss, obesity, polydactily, kidney abnormalities and intellectual disability)." (PMID 31031802, 2019). "Defects in BBS10 cause Bardet-Biedl syndrome 10 (BBS10) [MIM: 615987], an autosomal recessive ciliopathy characterized by retinitis pigmentosa, obesity, kidney dysfunction, polydactyly, obsessive-compulsive behavior, and hypogonadism." (PMID 27788217, 2016). "Presence of non-synonymous DNA sequence variants was limited to Bbs10, a chaperonin-like protein and one of the major genetic sources of Bardet-Biedl syndrome in humans with characteristics including postnatal obesity and diabetes among others." (PMID 22723961, 2012). "However, in BBS No.10, three variants were found, two of which in BBS2 and BBS8 genes were classified as VUS (variant of uncertain significance) and one variant in BBS10 gene was described as likely benign, but potentially causative for Bardet–Biedl syndrome." (PMID 33138063, 2020). "In one patient (#61), besides a biallelic BBS10 variant, a pathogenic PKD2 variant was identified leading to a double genetic diagnosis (Bardet–Biedl syndrome and ADPKD)." (PMID 39384646, 2025). "Recessive forms of severe obesity were identified, caused by homozygous or compound heterozygous mutations in the following genes: LEP (leptin), LEPR (leptin receptor), BBS1 and BBS10 (Bardet–Biedl syndrome), and POMC (pro-opiomelanocortin)." (PMID 40149731, 2025). "For Bardet-Biedl syndrome, BBS1 was the most commonly mutated gene (52.6% of families), followed by BBS10 (21.1%)." (PMID 38189974, 2024). "The set of genes associated with Bardet-Biedl syndrome is represented in cluster A by the nodes BBS12, BBS10, and BBS7." (PMID 33805313, 2021). "The purpose of this study was to compare the natural history of visual function change in cohorts of patients affected with retinal degeneration due to biallelic variants in Bardet-Biedl syndrome genes: BBS1 and BBS10." (PMID 34940782, 2021). "After reevaluation, the clinical diagnosis for patient 2016090902 who carried the novel compound heterozygous mutations NM_024685.3:c.1063C>T:p.(Gln355Ter) and NM_024685.3: c.378G>A:p.(Trp126Ter) in BBS10, was revised to Bardet–Biedl syndrome." (PMID 30029497, 2018). "The BBS10 gene is related to the Bardet-Biedl syndrome, a rare autosomal recessive disease characterized by systemic abnormalities including progressive rod-cone retinal dystrophy, cognitive impairment, postnatal obesity, renal dysplasia, and polydactyly." (PMID 23365660, 2013). "In Group II, MKKS causes the McKusick-Kaufman syndrome characterized by genitourinary malformations (MIM#236700), and BBS10, and BBS12 Bardet-Biedl syndromes (BBS) type 10 (MIM # 615987) and 12 (MIM # 615989)." (PMID 33076433, 2020).
ciliopathy (12 papers, 2015 to 2025). A genetic disorder of the cellular cilia or the cilia anchoring structures, the basal bodies, or of ciliary function. "They suggest that an additional variant in the ciliopathy gene BBS10, only present in the fourth child, could explain the more severe phenotype." (PMID 35873489, 2022). "Two transgenic mouse lines mimicking retinal degeneration associated with ciliopathy of the photoreceptors, such as the Fam161atm1b/tm1b (Fam161a knockout) mouse and the Bardet Biedl Syndrom-10 (BBS10 KO mice), also presented isolated photoreceptors with high H3K27me3 level." (PMID 34502238, 2021). "As BBS10 is a key ciliopathy gene, and the cilium can serve as a node for signal transduction, it was conceivable that the phenotypes seen in our BBS10 hiPSCs were due to an inability to respond to the appropriate inductive cues." (PMID 31293383, 2019). "Biallelic mutations in the ciliopathy-associated genes AHI1, BBS10, IQCB1, and OFD1 were identified in single patients." (PMID 29974258, 2018). "Taken together, these results indicate that different ciliopathy-specific genes (BBS1, BBS7, BBS10 and TMEM216) modulate distinct aspects of apical–basal polarity of the RG scaffold and the integrity of the proliferative niche organization." (PMID 26206566, 2015). "Of the 30 ciliopathy genes tested, knockdown of four genes (BBS1, BBS7, BBS10 and TMEM216) resulted in disruption of the apical–basal polarity of RG cells." (PMID 26206566, 2015). "To determine whether our observed mechanisms might be reflected in a ciliopathy patient disease model, we generated urine-derived renal epithelial cell (UREC) cultures from a BBS10 patient with age and gender-matched control." (PMID 34580290, 2021).
Obesity (8 papers, 2012 to 2025). Accumulation of substantial excess body fat. "Loss-of-function mutations of Pcsk1, Cnr1, and Bbs10 contribute to the development of obesity-associated features including severe early-onset obesity, increased waist circumference and skin-fold thickness, and higher adiposity." (PMID 36284088, 2022). "Bbs10−/− mice developed obesity, retinal degeneration, structural defects in the glomeruli, polyuria associated with high circulating arginine vasopressin (AVP) concentrations, and vacuolated, yet ciliated, renal epithelial cells." (PMID 26273430, 2015). "In this present study, 3-month-old mice were used to clearly demonstrate that in absence of obesity Bbs10 inactivation has no major impact on renal function." (PMID 26273430, 2015). "As Cadh16-Cre expression targets specifically the renal epithelial cells, no other characteristic BBS phenotype like obesity or retinal degeneration was observed in the Bbs10 fl/fl; Cadh16Cre+/− mice (data not shown)." (PMID 26273430, 2015). "The Bbs10−/− mice recapitulated most clinical features of the human condition, ranging from early-onset obesity, retinal degeneration and renal dysfunction whereas the Bbs10 fl/fl; Cadh16Cre+/− mice show neither detectable renal defect at 3 months nor any other noticeable manifestations." (PMID 26273430, 2015).
retinal degeneration (8 papers, 2015 to 2025). Degeneration of the retina. "Patients with mutations in BBS1 generally present later than patients with mutations in BBS10, owing to a milder phenotype and a later onset of retinal degeneration." (PMID 35484558, 2022). "Retinal degeneration appears earlier and is more severe in BBS10 cases as compared to those with BBS1 variants." (PMID 34940782, 2021). "While our findings highlight the potential of NAC as a therapeutic approach for BBS10-related retinal degeneration, further studies are needed to explore the underlying mechanisms, including the role of mitochondrial function, protein misfolding, and cell death pathways." (PMID 41001250, 2025). "The absence of the b-wave phenotype has not been previously reported in the Bbs10−/− model, and it provides new insight into the nature of retinal degeneration in BBS10-related diseases." (PMID 41001250, 2025). "A retrospective study of 67 individuals with BBS caused by variants in BBS1 or BBS10, recruited from six countries, revealed that the onset and progression of retinal degeneration occur earlier and faster in BBS10-related BBS than in BBS1-related BBS." (PMID 40087798, 2025). "This study utilizes Bbs10−/− mice to assess the effect of NAC supplementation on retinal degeneration." (PMID 41001250, 2025). "The fidelity of the phenotype with respect to endpoints similar to those used in humans makes this model ideal for testing the ability of preclinical treatments to slow or reverse retinal degeneration in BBS10." (PMID 36125046, 2022). "In conclusion, a knockout mouse model of BBS10 recapitulates the retinal degeneration in human patients and shares features of that condition." (PMID 36125046, 2022). "Recently, it was reported that, in BBS10, the onset and progression of retinal degeneration occur earlier and faster, respectively, than in BBS type 1 (BBS1), another common subtype." (PMID 36125046, 2022). "Comparison to Bbs1M390R/M390R, a mouse model of BBS1, demonstrated that the retinal degeneration in the BBS10 mouse model is more severe." (PMID 36125046, 2022). "This international collaborative effort allowed collection of data from patients with retinal degeneration and biallelic variants in the two most commonly involved BBS genes; BBS1 and BBS10 (hereon referred to as patients with BBS1 and patients with BBS10)." (PMID 34940782, 2021). "Our hypothesis is that BBS10 dysfunction leads to retinal degeneration and synaptic dysfunction, which may be ameliorated by reducing oxidative stress using NAC." (PMID 41001250, 2025). "This highlights a potential therapeutic target for BBS10-related retinal degenerations: preserving synaptic function may be as crucial as preventing photoreceptor degeneration." (PMID 41001250, 2025). "The natural history of the BBS1 and BBS10-related retinal degeneration remains somewhat incomplete as in many cases the age at which the ERG became nondetectable could not be captured and was possibly earlier than documented." (PMID 34940782, 2021). "Strengths of our study include the large, balanced, cohort size of genotyped patients, the report of a novel COD phenotype in 3 patients with BBS10-related retinal degeneration, the longitudinal data available and that the data was captured at a wide range of ages." (PMID 34940782, 2021). "Thus, for the three largest subgroups of patients BBS10 (20 patients), BBS1 (15 patients) and BBS9 (five patients) there is a similar pattern of retinal degeneration." (PMID 35886001, 2022).
hypogonadism (4 papers, 2016 to 2024). A disorder characterized by decreased function of the gonads. "Patients with renal anomalies should therefore be screened mainly in BBS10, BBS12, BBS6 and those with hypogonadism for variants in BBSome genes." (PMID 31196119, 2019).
Insulin resistance (4 papers, 2015 to 2024). Increased resistance towards insulin, that is, diminished effectiveness of insulin in reducing blood glucose levels. "Our results demonstrate that patients with mutations in BBS10 have significantly higher levels of C-peptide indicating insulin resistance, supporting the suggestion that they are at higher risk of cardiovascular disease than patients with mutations in BBS1." (PMID 24611735, 2015). "In addition, some studies have observed lower insulin resistance measured by HOMA-IR and lower abdominal fat index for variants of the BBS1 gene compared to the BBS10 gene." (PMID 33138063, 2020).
cone dystrophy (3 papers, 2021 to 2023). An inherited ocular disorder characterized by the loss of cone cells, the photoreceptors responsible for both central and color vision. "The BBS10 retinal phenotype can manifest as cone-radicular dystrophy or even isolated cone dystrophy." (PMID 37762059, 2023). "The retinal phenotype of BBS1 is typically described as RP-like rod-cone dystrophy; however, BBS10 may occur as a cone-rod dystrophy, or even an isolated cone dystrophy." (PMID 36125046, 2022).
cone-rod dystrophy (3 papers, 2021 to 2022). Inherited retinal dystrophies that belong to the group of pigmentary retinopathies. "A total of 16 patients (26%) were found to have a cone or cone-rod dystrophy, but it appears to be distributed evenly between BBS subtypes (3/15 BBS1, 2/3 BBS2, 3/3 BBS3, 1/5 BBS9, 5/20 BBS10, and 2/3 BBS12)." (PMID 35886001, 2022). "Additionally, a mouse knockout model of BBS5 developed a cone-rod dystrophy as well as displayed mislocalization of cone-specific proteins such as OPN1SW, OPN1MW and GNAT2; we report that OPN1MW and GNAT2 are mislocalized in Bbs10−/− mice." (PMID 36125046, 2022).
renal failure (3 papers, 2016 to 2020). "Moreover, in other patients from the study group, a relationship between mutations in the BBS10 gene and the occurrence of renal impairment was also observed (seven patients with renal failure, three of them with variants in the BBS10 gene)." (PMID 33138063, 2020). "Clinicians should also closely monitor patients harbouring mutations in BBS10, BBS12, BBS6 to favour early detection of those with renal anomalies, at risk of kidney failure and sudden death." (PMID 31196119, 2019).
Retinal dystrophy (3 papers, 2017 to 2024). Retinal dystrophy is an abnormality of the retina associated with a hereditary process. "However, retinal dystrophy was less severe in patients with BBS1 than in those with BBS10 variants." (PMID 28143435, 2017).
retinitis pigmentosa (3 papers, 2016 to 2024). Retinitis pigmentosa (RP) is an inherited retinal dystrophy leading to progressive loss of the photoreceptors and retinal pigment epithelium and resulting in blindness usually after several decades. "Patient two had a clinical diagnosis of retinitis pigmentosa and the Invitae kit reported BBS10, CA4, and NPHP1 as VUS; BG reported RCBTB1 and CA4 as VUS." (PMID 38892829, 2024).
morbid obesity (2 papers, 2016 to 2025). An excess of body weight, normally defined as an individual with a body mass index greater than 35 or a body weight greater than one hundred percent of ideal body weight. "Significant adiposity has been described in BBS10-related BBS; six of our ten participants with morbid obesity had BBS10-related BBS, while three had BBS1-related BBS." (PMID 40087798, 2025).
myopia (2 papers, 2021 to 2025). "For example, individuals with BBS1 mutations exhibited a mix of myopia and hyperopia, while those with BBS10 mutations were predominantly myopic with significantly higher rates of myopia compared to BBS1." (PMID 40731764, 2025). "For patients with BBS10, myopia was present in 16 (69%) of the 27 documented cases, whereas emmetropia was only seen in 3 (13%) and astigmatism was observed in about half (46%)." (PMID 34940782, 2021).
Nystagmus (2 papers, 2017 to 2022). Rhythmic, involuntary oscillations of one or both eyes related to abnormality in fixation, conjugate gaze, or vestibular mechanisms. "We did find a significant difference between BBS gene-association with respect to the occurrence of nystagmus (p = 0.005), with 68% of BBS10 patients suffering from nystagmus and only 21% of those with BBS1." (PMID 35886001, 2022). "We found that three of the four patients with biallelic variants in BBS10 showed a BCVA of light perception; the remaining one had nystagmus associated with exotropia." (PMID 28143435, 2017).
chronic kidney disease (1 paper, 2023). Impairment of the renal function secondary to chronic kidney damage persisting for three or more months. "Patient Xiry presented with late-stage chronic kidney disease (CKD) and had a sibling with mutant BBS10 and end stage renal failure (ESRF)." (PMID 37333983, 2023).
cyst (1 paper, 2015). A sac-like closed membranous structure that may be empty or contain fluid or amorphous material. "Moreover, cyst was undetectable in both Bbs10−/− and the Bbs10 fl/fl; Cadh16Cre+/− kidneys." (PMID 26273430, 2015).
developmental delay (1 paper, 2021). "The most prevalent extraocular features were digital anomalies (postaxial polydactyly, syndactyly, or brachydactyly), present in 96% of patients with BBS1 and 82% of patients with BBS10; followed by developmental delay, poor coordination, and kidney and liver anomalies." (PMID 34940782, 2021).
metabolic syndrome (1 paper, 2025). A cluster of metabolic risk factors for CARDIOVASCULAR DISEASES and TYPE 2 DIABETES MELLITUS. "Comparisons of patients with variants in BBS1 vs BBS10 have found BBS10 pathogenic variants to result in an increased disease severity as identified through increased incidence and risk for kidney disease, metabolic syndrome, CVD, and severity of childhood obesity." (PMID 39919037, 2025).
Polyuria (1 paper, 2015). An increased rate of urine production. "All together these data demonstrate that the specific inactivation of Bbs10 in the renal epithelial cells does not induce polyuria and the associated high AVP circulating levels." (PMID 26273430, 2015). "Based on these findings, we hypothesized that the BBS-induced polyuria is not simply related to the absence of BBS10 in the renal epithelium but is the result of more complex interactions between several pathways being impacted in the Bbs10−/−." (PMID 26273430, 2015).
renal dysfunction (1 paper, 2017). "The three BBS10-mutated patients we analyzed have renal dysfunction." (PMID 28143435, 2017).
kidney disease (7 papers, 2022 to 2025). "In a study of 350 individuals with BBS in the United Kingdom, approximately 50% had a BBS1-related disorder, which was associated with less severe kidney disease than, for example, BBS10-related BBS." (PMID 40087798, 2025). "The present study confirms that severe kidney disease is more commonly identified in patients with pathogenic variants in BBS10 compared to BBS1." (PMID 35112343, 2022). "Kidney disease has been described as more prevalent in BBS2-, BBS7-, and BBS9-related BBS, as well as in BBS6-, BBS10-, and BBS12-related BBS." (PMID 40087798, 2025).
cardiovascular disease (2 papers, 2015 to 2022). "Patients with missense mutations in BBS1 have lower biochemical cardiovascular disease markers compared with patients with BBS10 and other BBS1 mutations." (PMID 24611735, 2015). "This suggests that patients with missense mutations in BBS1 may be at lower risk of cardiovascular disease than patients with BBS10 or other mutations in BBS1." (PMID 24611735, 2015). "Generally, BBS10 and BBS2 patients have been reported as having more severe features than BBS1 with lower risk of cardiovascular disease." (PMID 35886001, 2022).
tumor (2 papers, 2017 to 2023). "In our study, we found that the expression of the LINC02407 target gene, BBS10, correlated positively with neutrophils but negatively with T cells CD8, suggesting that LINC02407 may also help regulate the tumor microenvironment of PTC." (PMID 36928327, 2023).
degenerative disease (1 paper, 2025). "Since BBS10 is a degenerative disease, we also quantified the thickness of the ONL to correlate the difference in presynaptic terminals between phenotypes with the number of photoreceptors." (PMID 41001250, 2025).
BBS10 also shares sentences with these, for which no sentence is quoted: Bardet-Biedl syndrome 10 (3 papers); Cognitive impairment (2); polydactyly (2); type 2 diabetes (2); Astigmatism (1); Ataxia (1); Barrett esophagus (1); breast carcinoma (1); cancer (1); chronic obstructive pulmonary disease (1); Compulsive behaviors (1); diabetes (1); end stage renal failure (1); Exotropia (1); Hearing impairment (1); Hypertension (1); Intellectual disability (1); Joubert syndrome (1); Liver fibrosis (1); lung fibrosis (1); neurodevelopmental disorder (1); Onset (1); psoriasis (1); renal dysplasia (1); Senior-Loken syndrome (1); syndactyly (1); Truncal obesity (1); Usher syndrome (1).